RNU6-841P (RNA, U6 small nuclear 841, pseudogene)
Gene: Small nuclear RNA gene on chromosome 19 (49,764,524 to 49,764,630, reverse strand). Ensembl gene ENSG00000206599.
Homologues: Orthologues: chimpanzee U6 (99% identical), mouse Gm24661 (75% identical), rat LOC120099051 (67% identical). Paralogues in human: RNU6-25P (88% identical), RNU6-1 (87% identical), RNU6-2 (87% identical), RNU6-3P (87% identical), RNU6-49P (87% identical), RNU6-4P (87% identical), RNU6-5P (87% identical), RNU6-6P (87% identical), RNU6-9 (87% identical), RNU6-10P (86% identical), RNU6-12P (86% identical), RNU6-13P (86% identical), and 1288 more.